BLM (BLM RecQ like helicase)
Diseases named in the same sentence as BLM in open-access papers (continued):
Sharing a sentence is not in itself a finding about the gene and the disease.
cancer (continued). "However, in addition to mutations, BLM gene undergoes various types of alterations including increase in the copy number, transcript, and protein levels in multiple types of cancers." (PMID 33777104, 2021). "Thus, cancer cells overexpress BLM to increase their survival, which in turn has been linked to poor cancer prognosis." (PMID 34966786, 2021). "However, the molecular mechanism underlying the regulation of BLM in cancers remains largely elusive." (PMID 34606619, 2021). "BLM mutations can cause genome instability and increase the risk of cancer." (PMID 32762026, 2020). "Mutations altering BLM function are associated with highly elevated cancer susceptibility." (PMID 31828101, 2019). "However, co-segregation data between cancers and germline variants are needed to definitively assess the role of BLM and PRF1 genes in GC predisposition." (PMID 31514334, 2019). "We reviewed the pedigrees of women who carry the BLM mutation to see if there might be an excess of cancers at any site in first- or second-degree relatives." (PMID 31614901, 2019). "Finally, we sought loss of heterozygosity at the BLM locus in tumor tissues (given that LOH is a signature event in most cancer syndromes with homologous repair deficiency)." (PMID 31614901, 2019). "It is not clear if heterozygous carriers of BLM mutations are at increased cancer risk, and if so, whether BLM should be included in cancer test panels for clinical use." (PMID 31614901, 2019). "Evidence for this was shown in U2OS cells with BLM knocked down via shRNA and then transfected with an expression plasmid containing mutations in motif VI that have also been documented to occur in certain cases of human cancer." (PMID 28239445, 2017). "The absence of BLM activity leads to a DNA defect repair, which causes genomic instability with increased rates of chromosomal breakage, rearrangements, gene mutation, and increase of the risk of cancer development." (PMID 27597923, 2016). "Importantly, patients with mutated BLM helicase display genomic instability and a cancer predisposition, and they exhibit a cellular phenotype of elevated COs between sister chromatids, which potentially drives cancer by loss of heterozygosity." (PMID 27011106, 2016). "Mutations within the domain VI of BLM detected in human cancer samples demonstrate the functional importance of this domain, suggesting human tumorigenicity resulting from mtBLM may be at least partly attributed to mitigated FANCD2 activation." (PMID 27083049, 2016). "Defects in BLM are also associated with the cancer phenotype." (PMID 26877874, 2016). "Moreover, hereditary mutations and polymorphisms in helicases often predispose, in a heterozygous state, to cancer (e.g. mutations in BLM)." (PMID 25238049, 2014). "The hub transcript BLM (7th largest hub, 33 children) encodes a DNA helicase that is important for mitotic DNA replication and DNA repair, and is mutated in a broad range of cancers." (PMID 23324451, 2013). "Transgenic mouse model studies also support the hypothesis that carriers of a single defective BLM allele are cancer prone." (PMID 21050475, 2010). "Since mutations that alter BLM function are associated with elevated cancer susceptibility, we reasoned that genetic variants of BLM and other proteins that form a complex with BLM might affect the risk for different cancer forms." (PMID 19432957, 2009). "In AML/MDS, rs393974 (BLM) and rs6496724 (BLM) were also significantly associated with cancer risk." (PMID 19432957, 2009). "There are very few other studies of polymorphisms of the BLM-complex and cancer risk." (PMID 19432957, 2009). "All three of these rare human diseases are characterized by a predisposition to cancer and chromosome instability, but the clinical features and cellular phenotypes are different from each other, suggesting unique roles of BLM, WRN, and RECQ4 helicases as tumor suppressors." (PMID 18074021, 2007).
cancer (continued). "Second, overexpression of TRF2 in telomerase-positive cancer cells caused replication fork stalling at telomeres and induced the formation of telomeric ultrafine bridges, which may also be explained by compromised BLM function." (PMID 39652599, 2024). "Moreover, a total of 2785 patients from nine immunotherapy studies were analyzed to reveal the role of BLM mutation in immunotherapy efficacy, and the results showed that BLM mutation was related to improved survival after immunotherapy across multiple cancers." (PMID 38124443, 2023). "However, loss-of-heterozygosity in BLM-deficient cells is rare, suggesting other cellular functions of BLM that may contribute to increased predisposition to cancer." (PMID 35267530, 2022). "Additionally, it has been postulated that non-sense SNP-mediated aberrant BLM activity or its high mRNA expression levels could confer genomic instability in humans, predisposing them to different cancer types." (PMID 33777104, 2021). "Interestingly, we found that BLM mRNA overexpression is associated with different types of cancers." (PMID 32704157, 2020). "Understanding the mechanism by which BLM attenuates tumor susceptibility will aid in our fundamental understanding of its roles in maintaining genomic stability and suggest new strategies for cancer prevention involving direct regulation of DNA repair pathways." (PMID 27413734, 2016). "We observed increased lactate and lactylation levels in anthracycline-resistant cancer cells and proposed a novel mechanism by which hyperlactylation of BLM by AARS1 promoted anthracycline resistance by activating HR repair in cancer cells." (PMID 40634292, 2025). "BLM-WT overexpression evidently rescued the viability and proliferation of T-resistant BKO cancer cells in response to THP treatment; however, K24R mutation impaired the effect of BLM." (PMID 40634292, 2025). "We subsequently revealed that BLM ubiquitination was suppressed in E-resistant cancer cells and that inhibition of BLM lactylation via a glycolysis inhibitor increased BLM ubiquitination; however, sodium lactate treatment had the opposite effect." (PMID 40634292, 2025). "Together with the mouse and human iPSC models, these studies suggest a vital role of BLM helicase in normal development and prevention of diseases like cancers." (PMID 40728512, 2025). "The expression of BLM is high in cancers such as lymphoma and carcinomas originated from prostate and epithelium." (PMID 40728512, 2025). "From the view that BS patients have high tendency to develop various types of cancer, BLM is regarded as a tumor suppressor." (PMID 40728512, 2025). "The dissection of BLM’s function in ALT and the mechanism of BLM inhibitors in ALT will guide future strategies to eliminate ALT-reliant cancers." (PMID 40025590, 2025). "Dominant cancer‐associated pathogenic and likely pathogenic variants were identified in BRCA1 and MET, and two patients were carriers of recessive pathogenic BLM variants." (PMID 39344744, 2025). "Combining chemotherapy and/or immunotherapy with BLM inhibitors, the improved survival rates observed provide further evidence of BLM’s role in cancer progression." (PMID 40728512, 2025). "Among the proteins required to sustain ALT-mediated telomere elongation in cancer cells, the Bloom syndrome DNA helicase BLM is particularly important." (PMID 39605432, 2024). "Their findings showed that Exo-BLM had high cancer targeting ability and enhanced antitumor activity, and reduced toxicity compared to free bleomycin in a mouse model." (PMID 38172932, 2024). "Although BLM has been identified as a potential drug target in cancer therapy, its molecular regulatory mechanisms remain inadequately elucidated." (PMID 38806577, 2024). "Some studies also indicate BLM overexpression as an adverse prognostic factor in cancer patient survival." (PMID 38124443, 2023).
cancer (continued). "Germline mutations in RECQL1, BLM, WRN and RECQL4 genes are manifested by genome instability and linked to the recessive autosomal syndromes and predisposition to cancer." (PMID 37169803, 2023). "Biallelic mutations in these RecQ homologs, WRN, BLM, and RECQL4, have been previously reported to be associated with rare human genetic diseases characterized by chromosomal instability and cancer susceptibility." (PMID 37180972, 2023). "DNA double-strand break misrepair is a potential driver of CIN and cancer predisposition as highlighted by mutations in BRCA1, ATM, NBS1 and BLM being causal in cancer syndromes associated with CIN." (PMID 36951111, 2023). "Disruption of BLM function in mice resulted in frequent sister chromatid exchange and developing cancer in heterozygous mutants or embryonic lethality of homozygous mice." (PMID 37169803, 2023). "In this review, we focus on the roles of RecQ helicases, particularly on the cancer-associated BLM, WRN, and RECQL4, and discuss their potential as targets for cancer treatment." (PMID 35267530, 2022). "Among these 28 P-proteins, we focused on the Bloom syndrome protein (BLM) as a putative SMYD3 interactor because of its involvement in cancer." (PMID 35495117, 2022). "In our cohort, fourteen patients harbored a monoallelic P/LPV associated with recessive disorders (NTHL1, RECQL4, ERCC3, FANCA, and BLM) and one patient harbored PV in a low penetrance cancer gene (TYR)." (PMID 36132150, 2022). "Biallelic, loss-of-function germline pathogenic variants in three of them, BLM, WRN, and RECQL4, have been linked to rare cancer-predisposing syndromes." (PMID 35782872, 2022). "Of the five different proteins in humans, RECQL1, BLM, WRN, RECL4, and RECQL5, three are associated with germline alterations associated with an increased risk of cancer." (PMID 35782872, 2022). "Among these five, mutations in BLM, WRN, and RECQL4 are associated with premature aging and a higher risk of developing cancers." (PMID 35267530, 2022). "Strikingly, biallelic mutations in 3 of 5 of these RecQ homologs — WRN, BLM, and RECQL4 — have been associated with rare genetic disorders in humans, characterized by chromosomal instability and cancer predisposition." (PMID 35025765, 2022). "Biallelic germline mutations in BLM, WRN, and RECQL4 have been linked to rare cancer-predisposing syndromes." (PMID 35782872, 2022). "PV were detected in 13 cancer predisposition genes including ATM (n=4), BLM (n=1), BRCA1 (n=1), BRCA2 (n=7), BRIP1 (n=1), CDKN2A (n=1), CHEK2 (n=9), FANCC (n=1), MUTYH (n=10), NBN (n=1), PALB2 (n=1), RAD51D (n=1) and STK11 (n=1)." (PMID 36091166, 2022). "Recent studies have shown that BLM is upregulated in many cancers including lung squamous cell carcinoma, colon adenocarcinoma, endometrial carcinoma, cervical squamous cell carcinoma, and endocervical adenocarcinoma." (PMID 35267530, 2022). "Remarkably, we identified mTOR, BLM, MET, AMPK, and p130 as new SMYD3 interactors implicated in cancer processes." (PMID 35495117, 2022). "BLM methylation was reduced in cancer tissues compared with the adjacent normal samples, which was in accordance with the observed upregulation of this real hub gene in CCA." (PMID 33828983, 2021). "This review focuses on delineating the functions of one of the RecQ helicase BLM with a particular emphasis on its dual role in cancer." (PMID 33777104, 2021). "A small, but unique group of 16 non-FAP mesenteric desmoid was found to harbor genetic alterations in cancer associated genes other than APC, including CHEK2, BLM, ERCC5, MSH6, and PALB2." (PMID 34359575, 2021).
cancer (continued). "Most efforts thus far have focused on understanding the role of the Bloom syndrome DNA helicase BLM as a recombination factor in maintaining genome stability and suppressing cancer." (PMID 33495511, 2021). "In order to address these questions, it becomes imperative to investigate the molecular mechanisms involved in the de-regulation of the BLM gene specifically in the cancer cells to gain insights into its “dual role” in humans." (PMID 33777104, 2021). "More importantly, BLM inhibition by ML216 also increased the radiosensitivity of olaparib to A549 cancer, both in vitro and in vivo." (PMID 34846107, 2021). "Synthetic lethality analysis implicates BLM as a promising target in a range of cancers with defects in the DNA damage response; however, selective small molecule inhibitors of defined mechanism are currently lacking." (PMID 33647232, 2021). "BLM was found to be a potential target for cancer therapy due to its synthetic lethality in a range of cancers with defects in DNA damage response." (PMID 34846107, 2021). "BLM, WRN, and RECQL4 are associated with genetic disorders characterized by chromosomal instability, premature aging, and increased susceptibility to cancer." (PMID 33824465, 2021). "A class of isaindigotone derivatives as novel BLM inhibitors was reported to disrupt the BLM/DNA interactions and regulate HR repair by promoting accumulation of Rad51 in cancer cells." (PMID 34846107, 2021). "Heterozygous variants in BLM and FANCB (in females) have the potential to be associated with increased susceptibility to cancer." (PMID 31937788, 2020). "Collectively, these findings suggest that SLX4IP expression and its association with ALT phenotypes influence cancer cell susceptibility to the anticancer activities of ATR and BLM inhibitors." (PMID 32071280, 2020). "It is known that the level of BLM expression is regulated differently during cell cycle stages and is expressed at high levels in cancer cells." (PMID 32565735, 2020). "As other studies have found, cancer cells have high cytoplasmic BLM, and it would be interesting to experimentally validate the nsSNPs with BLM protein localization in cancer cells." (PMID 32704157, 2020). "Mutations in human RecQ helicases BLM, WRN and RecQL4 cause incurable disorders characterized by genome instability, increased cancer predisposition and premature adult-onset aging." (PMID 32085395, 2020). "As a promoter of DNA replication, the high BLM expression satisfies the high replicative demands of cancer cells, while the ability of BLM to maintain genomic stability confers survival advantages to these malignant cells." (PMID 31210839, 2019). "RECQL is one of the five RECQ genes, three of which (BLM, WRN and RECQL4) have been implicated in genetic disorders with increased cancer risk." (PMID 30610487, 2019). "Searching for other proliferation genes resulted in finding EXO1, MCM10, GINS2, CDT1, ORC6L, and BLM had the same pattern indicating they are most likely necessarily highly transcribed in cancer." (PMID 31857847, 2019). "An analysis of the DEPs involved in the regulation of protein phosphorylation revealed high BLM expression in PC cancer tissue." (PMID 31210839, 2019). "Molecular defects in the RecQ helicases give rise to genomic instability, and mutations in WRN, BLM, and RECQL4 are linked to hereditary diseases characterized by accelerated aging or associated with cancer." (PMID 29998112, 2018). "We identified deletions overlapping two known cancer susceptibility genes, (BRCA1 and BLM), and a duplication overlapping SMARCB1, associated with risk." (PMID 28302160, 2017). "Functional autosomal recessive loss of BLM, WRN and RECQL4, results in hereditary human syndromes characterized by cancer predisposition and premature aging (Bloom's, Werner's, and Rothmund-Thomson's syndromes, respectively)." (PMID 27764811, 2016).
cancer (continued). "The Groden laboratory has studied BLM (and WRN) for many years and we use BS as a paradigm for understanding how DNA repair deficiency impacts both growth and cancer." (PMID 27413734, 2016). "Mutations in three of the five human RECQ helicases, BLM, WRN and RECQ4, lead to genetic disorders as Bloom, Rothmund-Thompson and Werner’s syndromes that are associated with cancer predisposition, premature ageing and developmental abnormalities." (PMID 26877874, 2016). "Their analysis identified copy number variation in BRCA1 and BLM, two genes found to be critical nodes in our sub-networks, as factors related to sensitivity to metformin in cancer tissue." (PMID 26841718, 2016). "It has been reported that inhibition of BLM leads to increased DNA double-stranded breaks and apoptosis of cancer cells." (PMID 25477524, 2015). "RECQL is considered to be genome caretaker, and mutations in three of five RecQ genes, BLM, WRN and RECQ4 are associated with cancer predisposition and/or premature aging." (PMID 25945795, 2015). "These two diseases are characterized by a high frequency of cancer predisposition, illustrating the primary importance of WRN and BLM in preventing tumorigenesis." (PMID 25400656, 2014). "Mutations in three of which including BLM, WRN and RecQL4 have been linked to distinct human disorders with common characteristics of premature aging and cancer predisposition." (PMID 23894508, 2013). "Defects in the genes of three of the five human DNA helicases, BLM, WRN and RECQ4, are responsible for distinct genetic disorders associated with cancer predisposition." (PMID 21752281, 2011). "Mutations in three of the five known RecQ family members in humans, BLM, WRN and RecQ4, lead to disorders that are characterized by predisposition to cancer and premature aging." (PMID 19572017, 2009). "BLM and WRN, human RecQ helicases associated with cancer and disease, have both been shown to associate with duplex telomere repeat binding protein TRF2 in vivo, and BLM co-localizes to telomeric foci exclusively in ALT cells." (PMID 15642092, 2005). "While carriers of pathogenic germline BLM variants do not exhibit a clear cancer risk, the variants likely increase cancer susceptibility when combined with other risk factors." (PMID 39344744, 2025). "Furthermore, combination treatment with irinotecan and EPI suppressed DNA end resection and HR repair in BLM-WT-overexpressing cancer cells, increasing the degree of DNA damage in this group." (PMID 40634292, 2025). "In some cancers, however, BLM is required for their uncontrolled proliferation." (PMID 40728512, 2025). "This is even more true because some of the predisposing variants may carry a risk for other cancers or diseases later in life, examples being mutations in BRCA2, STK11, BLM, and CDKN2A, among other genes." (PMID 40340749, 2025). "For example, Hereditary Breast and Ovarian Cancer (HBOC) syndrome caused primarily by variants in BRCA1/2 which have overlapping functions with BLM, is associated with increased cancer risk without syndromic features." (PMID 37594403, 2023). "The median age for cancer diagnosis across the BRCA1/2 mutation carriers was 46 years, in the CHEK2 group it was 42.5 years, 44.8 years for ATM, 48.6 years for PALB2, 44 years for MUTYH, and 45.6 years for BLM." (PMID 38201513, 2023). "Such different localisation indicates distinct functions of BLM in malignant tumours." (PMID 37169803, 2023). "Moreover, it was found that RECQs exhibited a notable variation in prognosis across different types of cancers, with RECQL, BLM, and RECQL4 showing promising diagnostic potential in LIHC." (PMID 37626815, 2023). "In addition, in cancer cells where an alternative lengthening of telomere (ALT) mechanism is active, BLM is associated with the ALT-associated PML NBs (APBs) and plays a critical role in ALT58." (PMID 37777511, 2023).